APOBEC3A (apolipoprotein B mRNA editing enzyme catalytic subunit 3A)
Diseases named in the same sentence as APOBEC3A in open-access papers (continued):
Sharing a sentence is not in itself a finding about the gene and the disease.
cancer (continued). "The results demonstrate that APOBEC3A is the major driver of clustered and non-clustered APOBEC3 mutational signatures in cancer cell lines in which results from surrogate assays of APOBEC3 activities recapitulated current debates in the field." (PMID 35859169, 2022). "An increase in the expression of APOBEC3B—but not APOBEC3A—was observed in cancers with ecDNA compared to samples without ecDNA (3.1-fold; q-value < 1 × 10−5)." (PMID 35140399, 2022). "APOBEC3A and APOBEC3B often function as oncogenes in these cancers." (PMID 35902635, 2022). "Comparison of gene expression between the editing-positive and -negative samples showed that APOBEC3A was the only CDA gene whose expression was upregulated in the editing-positive samples in all three cancers." (PMID 25898173, 2015). "Also, our PCa patients showed no APOBEC3A and APOBEC3B germline predispositions, as previously reported in other cancers, including rs12628403, rs1014971." (PMID 41282084, 2025). "While not completely understood, APOBEC3A is a multifaceted DNA/RNA editing enzyme that can provide a defense against viruses, but its non-discriminatory editing also contributes to cancer disease progression through aberrant editing of the genome and potentially of mRNAs." (PMID 38976757, 2024). "Expression of innate immune system markers (APOBEC3A/B), DNA repair genes (BRCA1, BRCA2, PALB2, RAD51), cell cycle genes (CCNA2 and CCNE1), a cell proliferation gene (MELTF), and a T-cell regulator (Treg) marker (FOXP3) was elevated in cancer compared to precancer and controls." (PMID 39672307, 2024). "Whereas many studies have focused on the molecular roles of APOBEC3B, and to some extent APOBEC3A, possible cumulative effects of action of APOBEC3A, APOBEC3B, UNG, REV1, and FHIT on generation of APOBEC3B-like mutation motifs and on drug sensitivity in cancer have not been clearly elucidated." (PMID 29642934, 2018). "APOBEC3B expression also had the strongest correlation with mutation counts in RCC as opposed to other cancer categories; however, such correlations for APOBEC3B were somewhat weaker and less significant (ρ ≤ 0.86, padj ≥ 0.16) than those for APOBEC3A (data not shown)." (PMID 29642934, 2018). "However, we hypothesize that the process outlined leads to a tumor defined by APOBEC3A/B mutagenesis but where no virus is present in the final cancer." (PMID 41337590, 2025). "Accurately determining the conditions under which APOBEC3A and APOBEC3B are expressed in normal and cancerous tissues represents a key challenge in building our understanding of how APOBEC-mediated mutagenesis occurs, and how they might be targeted for cancer treatment." (PMID 39548236, 2025). "Although identification of specific inhibitors against APOBEC3A and 3B are still ongoing, the development of APOBEC3A-ssDNA and APOBEC3B-ssDNA co-crystal structures may be helpful for developing structure-based molecule inhibitors that could be useful in cancer therapy." (PMID 34578402, 2021). "The absence of APOBEC3A in basal and terminally differentiated cells suggests it, too, is subject to transcriptional repression; another mode of regulation that, if disrupted, could enable bursts of mutagenic APOBEC activity in cancer cells." (PMID 39548236, 2025).
tumor (51 papers, 2013 to 2026). "APOBEC3A-induced mutagenesis occurs in episodic bursts that rapidly elevate mutation rates over short intervals, providing tumor cells with evolutionary advantages yet causing severe genomic damage." (PMID 41278855, 2025). "Prevention of genotoxicity by SMC5/6 appears to be specific to APOBEC3A among tumor-associated cytosine deaminases." (PMID 38886582, 2024). "Specifically, it has been shown that APOBEC3A induces the polarization of monocytes/macrophages, including tumour-associated macrophages (TAMs), toward a pro-inflammatory M1-like phenotype through its RNA editing activity." (PMID 35955853, 2022). "The human APOBEC3A (A3A) cytidine deaminase is a powerful DNA mutator enzyme recognized as a major source of somatic mutations in tumor cell genomes." (PMID 34403699, 2021). "Here the authors present a computational approach to identify the RNA mutations specifically driven by APOBEC3A, and developed an RNA mutation-based assay to quantify ongoing APOBEC3A activity in tumor cells." (PMID 32532990, 2020). "However, tumor cells hijack these endogenous mutators, particularly APOBEC3A and APOBEC3B, to fuel genetic diversification and to adapt rapidly under selective pressures." (PMID 41278855, 2025). "Importantly, we determine that APOBEC3B-induced mutations in hairpin-forming sequences within tumor genomes differ from the DNA stem-loop sequences mutated by APOBEC3A." (PMID 38499542, 2024). "Therefore, APOBEC3A/G DNA editing is likely a factor in pathogenic SNPs and the creation of variant proteins beyond its known activity in neoplasms." (PMID 37577456, 2023). "These mutations likely influence tumor evolution through the activation of oncogenes and inactivation of tumor suppressor genes, and in-depth characterization of this mechanism has highlighted APOBEC3A and APOBEC3B as the main mutagens in this context." (PMID 36980505, 2023). "Although APOBEC-mutational signature is found in tumor tissues of multiple cancers, how a common germline APOBEC3A/B deletion affects the mutational signature remains unclear." (PMID 31533728, 2019). "Therefore, the immunosuppressive effect of APOBEC1 in the PAAD tumor microenvironment and the genomic instability caused by the high expression of APOBEC3A/3G/3H in PAAD tissues may be important factors in the occurrence and development of PAAD." (PMID 36339709, 2022). "It is important to note the limitations of performing this analysis in bulk RNA-seq data, in which APOBEC3A expression in cell types (e.g. tumour-resident macrophages or infiltrating neutrophils) that do not express GRHL3 will influence these correlations." (PMID 39548236, 2025). "Two of the eleven members of the APOBEC family, APOBEC3A (A3A) and APOBEC3B (A3B) are responsible for the majority of the APOBEC mutational signatures identified in tumor cells." (PMID 38499542, 2024). "In a combined analysis of multiple tumor types, APOBEC3B expression was strongly associated with a higher APOBEC3-induced mutation load; APOBEC3A, APOBEC3F, and APOBEC3G showed similar but weaker correlations." (PMID 36978147, 2023). "Here, we investigate the molecular mechanism of APOBEC3A-driven tumor development using the murine Fah liver complementation and regeneration system." (PMID 37298259, 2023). "Among the APOBEC3 enzymes, APOBEC3A (A3A) and APOBEC3B (A3B) are the most likely sources of the overall APOBEC‐driven mutations in human tumours." (PMID 36416305, 2023). "Correlation analysis between APOBEC3A/B genotypes and clinicopathological parameters of tumor samples positive for the presence of MMTV-like env gene demonstrate a correlation between the heterozygous genotype and lower age-at-diagnosis." (PMID 36980505, 2023). "Collectively, these results demonstrate that APOBEC3A is a “master driver” that fuels tumor formation through a DNA deamination-dependent mechanism." (PMID 37298259, 2023).
tumor (continued). "Recent murine studies have established cause-and-effect relationships, with both human APOBEC3A and APOBEC3B proving capable of promoting tumor formation in vivo." (PMID 37298259, 2023). "Second, we show that the catalytic glutamic acid residue of APOBEC3A (E72) is required for tumor formation." (PMID 37298259, 2023). "Third, we show that an APOBEC3A separation-of-function mutant with compromised DNA deamination activity and wildtype RNA-editing activity is defective in promoting tumor formation." (PMID 37298259, 2023). "Tumor volumes and weights were smaller in the APOBEC3A overexpression group than in the control group." (PMID 38021159, 2023). "In contrast, our study found an association between APOBEC3A expression and longer OS, which would assign tumor-suppressive functions to APOBEC3A in PSC." (PMID 35902635, 2022). "APOBEC3A and 3B play a significant role in the malignant progression and cell differentiation within the tumor microenvironment." (PMID 35673559, 2022). "In fact, recent studies have exposed the importance of APOBEC3A, not only in cancerous cells but also in stromal cells of the tumour microenvironment (TME)." (PMID 35955853, 2022). "The known effect of APOBEC3A is leading to DNA double-strand breaks and DNA damage, thereby disrupting cell cycle of tumor cells." (PMID 34745121, 2021). "Secondly, the CIBERSORT method was then performed to investigate the relationship between APOBEC3A and specific immune cells, which calculated the proportion of 22 different tumor-infiltrating immune subtypes." (PMID 34745121, 2021). "Our study presents a strategy to follow the dysregulation of APOBEC3A in tumors, providing opportunities to investigate the role of APOBEC3A in tumor evolution and to target the APOBEC3A-induced vulnerability in therapy." (PMID 32532990, 2020). "In a mouse xenograft model, high expressing, but not low expressing APOBEC3A-exposed cells caused increased tumor progression." (PMID 41675410, 2026). "In HNSCC, we find evidence of GRHL3 activity and APOBEC3A in a subpopulation of tumour cells undergoing DNA replication; the context in which mutagenic APOBEC activity is postulated to occur due to deamination of lagging strand ssDNA exposed at the replication fork." (PMID 39548236, 2025). "GRHL3 activity and APOBEC3A expression were frequently highest near the tumour surface." (PMID 39548236, 2025). "The S-phase tumour cells with high APOBEC3A expression were all designated a binary GRHL3 activity score of ‘on’, suggesting that GRHL3 can drive APOBEC3A expression in tumour cells undergoing DNA replication, potentially causing APOBEC3A-mediated mutagenesis." (PMID 39548236, 2025). "Along with APOBEC3A, APOBEC3B has been implicated in tumor mutagenesis." (PMID 38886582, 2024). "Additional genes involved in the BER pathway exhibited a similar pattern, with positive association with APOBEC3B but not APOBEC3A in tumor samples." (PMID 38617360, 2024). "Overexpression of APOBEC3A inhibited tumor formation in the mouse model." (PMID 38021159, 2023). "Additionally, the APOBEC3B expression level was higher than that of APOBEC3A in most frozen tumor tissue samples." (PMID 35592333, 2022). "Our finding of their co-upregulation with APOBEC3A in the newly developed tumor under CPI suggests they may promote tumor progression via upregulating APOBEC3A activity, further inducing APOBEC3A mutagenesis." (PMID 36210388, 2022). "HEY cells that are transfected with APOBEC3A were almost stained by the dye of anti-H2Ax antibody, suggesting that APOBEC3A could contribute to the DNA damage in tumor cells thereby playing a role of depressing tumor development." (PMID 34745121, 2021). "Analyzing the 4-nucleotide context of 788 WGSs from 27 tumor types with evidence of APOBEC activity enrolled within the PCAWG ICGC consortium, we observed a strong positive association between APOBEC3A/APOBEC3B ratio and APOBEC mutational burden (linear regression p < 0.0001)." (PMID 32317634, 2020).
tumor (continued). "Intriguingly, it has been postulated that APOBEC3A-mediated hypermutation could generate new tumour-specific antigens thereby enhancing the efficacy of immune stimulation therapies." (PMID 31019223, 2019). "However, how APOBEC3A/B enzymes affect tumor evolution in the presence of exogenous mutagenic processes is largely unknown." (PMID 40394004, 2025). "However, how APOBEC3A/B enzymes shape the tumor evolution in the presence of exogenous mutagenic processes is largely unknown." (PMID 38617360, 2024). "In addition, we could observe that patients that were negative for MMTV-like DNA and with a heterozygous genotype for APOBEC3A/B had a lower tumor stage compared to patients with a wild genotype." (PMID 36980505, 2023). "Besides, IL1B and CD80 were detected to be significantly increased in the HEY cells with APOBEC3A upregulation, indicating that APOBEC3A could accelerate the transformation of M0 macrophages to M1 in tumor immune microenvironment of OC patients." (PMID 34745121, 2021). "Staining the same TMA with an antibody that binds to APOBEC3A, APOBEC3B and APOBEC3G revealed characteristic nuclear APOBEC3B expression in tumour cells (Fig. EV4)." (PMID 39548236, 2025). "Cytotoxicity of APOBEC3A activity upon ATR inhibition illustrates a synthetic lethal interaction and the essential nature of DNA damage responses in tumor cells undergoing mutagenesis." (PMID 38886582, 2024). "We extract signatures of RNA single-base substitutions and link their aetiology to the activity of the RNA-editing enzymes ADAR and APOBEC3A, thereby revealing otherwise undetected ongoing APOBEC activity in tumours." (PMID 37046093, 2023). "Among the gene expressions, it was found that the expression of APOBEC3A and APOBEC3B was significantly higher in tumor tissues than in normal tissues." (PMID 35510248, 2022). "APOBEC3A expression level was similar between the 2 sample sources, but the APOBEC3B expression level was higher in frozen tumor tissue than in the FFPE sample." (PMID 35592333, 2022). "In the dataset with the largest number of samples (GSE117556), RNA was extracted from FFPE tumor tissue; therefore, APOBEC3A and APOBEC3B expression levels were analyzed in different samples in GSE19246, which contains both frozen and FFPE tumor tissue." (PMID 35592333, 2022). "Our results revealed that all APOBEC3 molecules were upregulated in tumor cells except for APOBEC3A, which was dramatically decreased in DLBC and THYM tumor cells." (PMID 34638749, 2021). "Despite these limitations, we observed a number of correlations, e.g., those between APOBEC3A and APOBEC3B expression levels, that have also been reported in patient tumor samples." (PMID 29642934, 2018). "And the expression levels of APOBEC3A and APOBEC3B were significantly lower in tumor tissues than in morphologically normal operative margin tissues." (PMID 25502777, 2014). "In MMTV-like negative samples, APOBEC3A/B deletion was negatively correlated with tumor stage while being positively correlated with estrogen receptor expression." (PMID 36980505, 2023). "Although not in the tumor itself, increased APOBEC3A expression has been shown to shift macrophage polarization to a pro-inflammatory, immune-activating state." (PMID 36978147, 2023). "The pentanucleotide regression finds enrichment of pyrimidines at position -2, supporting the role of the APOBEC3A enzyme rather than the APOBEC3B paralog in mutagenizing this particular tumor." (PMID 35015788, 2022). "Following the co-expression and network analyses, this signature was found to be enriched for genes involved in the regulation of the stroma component of the tumor (TDO2, STEAP1) as well as Treg cells (SLC16A1, PRKAB1) and myeloid cell (APOBEC3A, MERTK, SNX29) subsets." (PMID 36216827, 2022).
tumor (continued). "In the tumour samples, the majority of epithelial (tumour) cells expressed neither APOBEC3A nor APOBEC3B at levels detectable by scRNA-seq, and the only datasets containing a significant number of cells expressing APOBEC3A and/or APOBEC3B were from HNSCC or ESCC." (PMID 39548236, 2025). "The fact that we only observed high APOBEC3A expression in a small minority of S-phase cells in our HNSCC samples is consistent with the proposed episodic nature of APOBEC-mediated mutagenesis, in which the chances of observing a mutagenic burst in the snapshot provided by a tumour biopsy are low." (PMID 39548236, 2025). "This leads us to speculate that APOBEC3A—having tumor-suppressive functions in HPV+ disease—is not responsible for APOBEC-induced mutational signatures correlated with worse outcomes in HPV+ PSCs." (PMID 35902635, 2022). "A significant and positive correlation of gene expression was found between UNG and APOBEC3B in both tumor subtypes (LAS: R=0.33 and P=8.8e-04; HAS: R=0.45 and P=1.5e-05), but not between UNG and APOBEC3A (LAS: R=-0.094 and P=0.36; HAS: R=0.046 and P=0.67)." (PMID 38617360, 2024). "Inducing APOBEC3A and APOBEC3B for tumor levels may not accurately mimic the carcinogenesis arising in pre-malignant tissues given their generally lower expression in normal tissues." (PMID 38254863, 2024). "While induction of PD-L1 by APOBEC3A would suggest a mechanism of immune evasion and resistance, such an effect should theoretically lead to increased sensitivity to CPI, which was not seen in this patient’s resistant tumor." (PMID 36210388, 2022).